IL4 (interleukin 4)
Diseases named in the same sentence as IL4 in open-access papers (continued):
Sharing a sentence is not in itself a finding about the gene and the disease.
placental insufficiency (1 paper, 2012). Failure of the placenta to deliver an adequate supply of nutrients and oxygen to the fetus. "Three of the proinflammatory : anti-inflammatory cytokine ratios are higher in IUGR with placental insufficiency; these are IL-12/IL-10 (P < 0.005), IL-12/IL-4 (P < 0.02), and IL-8/IL-10 (P < 0.01)." (PMID 22110537, 2012). "Three of the ratios are also higher in IUGR without placental insufficiency: IL-12/IL-10, IL-12/IL-4, and IL-8/IL-10." (PMID 22110537, 2012).
Pleuritis (1 paper, 2013). Inflammation of the pleura. "A similar negative regulatory role for IL-4 in Th1 recruitment to sites of inflammation was observed in a model of Th1-driven pleuritis where administration of IL-4 significantly blocked cell trafficking to the pleural cavity." (PMID 23991011, 2013).
pneumococcal meningitis (1 paper, 2012). An acute purulent infection of the meninges and subarachnoid space caused by Streptococcus pneumoniae, most prevalent in children and adults over the age of 60. "IL-1β, IL-2, IL-4, IL-10, IL-12p70, IL-17, RANTES, TNF-α, IL-18 and IL-33 were not significantly altered in the plasma of mice with pneumococcal meningitis compared to sham controls." (PMID 22455545, 2012). "IL-2, IL-4, IL-10, IL-12p70, IL-17, IFN-γ, TNF-α, IL-18 and IL-33 were not altered in brain homogenates of mice with pneumococcal meningitis compared to sham controls." (PMID 22455545, 2012).
pneumoconiosis (1 paper, 2011). An occupational lung disorder caused by inhalation of dust particles. "In the present study, we investigated the association between the potential functional polymorphisms in IL-4, IL-4R, and IL-13 and coal workers' pneumoconiosis (CWP) risk in a Chinese population." (PMID 21857939, 2011).
pneumonic plague (1 paper, 2020). A plague in which the bacteria have infected the lungs. "It was also reported that a live-attenuated ΔyscB mutant, which provides protection against bubonic and pneumonic plagues, induces elevated levels of IL-4." (PMID 33014895, 2020).
podoconiosis (1 paper, 2024). A disease of the lymphatic vessels of the lower extremities that is caused by chronic exposure to irritant soils. "On the other hand, the expression of IL-4 mRNA level was 1.8-fold higher in healthy controls compared to podoconiosis patients (p = 0.27)." (PMID 39591258, 2024).
polycystic ovaries (1 paper, 2022). "Inversely, IL-4, as representative of Th2 response was dropped below normal level, suggesting polarization of T cell response in polycystic ovaries." (PMID 34991678, 2022).
progeroid syndrome (1 paper, 2024). A group of rare genetic disorders which mimic physiological aging, making affected individuals appear to be older than they are. "Moreover, in Werner patients, another progeroid syndrome, a Th2-like secretory phenotype has been found with high serum levels of IL-4 and IL-10." (PMID 38474366, 2024).
prurigo (1 paper, 2023). A name applied to several itchy skin eruptions of unknown cause. "The expression of IL-4, IL-13, and IL-4 receptor (IL-4R) is upregulated in prurigo nodules, with IL-4 correlating with the intensity of itch." (PMID 38077377, 2023).
pterygium (1 paper, 2025). A wedge-shaped fibrovascular lesion arising from the bulbar conjunctiva and extending to the cornea. "Gene expression profiling of pterygium highlighted an IL-33 and IL-4 gene expression signature, along with an increased presence of M2 macrophages, emphasizing their role in promoting fibrosis—a hallmark feature of pterygium." (PMID 40243577, 2025).
rectal polyps (1 paper, 2022). "Significantly higher levels of IL-4, MIP-1β, FasL, and TGF-β1 were detected in rectal polyps." (PMID 36313365, 2022).
renal tubular acidosis (1 paper, 2023). A group of genetic disorders of the kidney tubules characterized by the accumulation of metabolically produced acids with elevated plasma chloride, hyperchloremic metabolic acidosis. "We consider that the activated T cells produce more IL-4, IL-10, IFN-γ and TNF-α during pSS complicated by renal tubular acidosis, leading to the activation of B cells and thus more autoantibodies." (PMID 37391717, 2023).
rhabdomyosarcoma (1 paper, 2021). A rare aggressive malignant mesenchymal neoplasm arising from skeletal muscle. "In rhabdomyosarcoma cells, IL4 and IL13 activate cellular proliferation through the JAK/STAT signaling pathway, and blocking IL4R with a neutralizing antibody suppressed tumor progression." (PMID 33419470, 2021). "In rhabdomyosarcoma cells, activation of IL4R with IL4 and IL13 ligands increased tumor growth through activation of STAT6, Akt, or MAPK pathways." (PMID 33419470, 2021).
salivary gland tumors (1 paper, 2025). "In patients with salivary gland tumors (WT and PA), various chemokines have been determined, including CCL28, CXCL10, CXCL12, CCL18, and CXCL1, as well as pro-inflammatory cytokines such as IL-1β, IL-6, IL-4, IL-17, and IL-33." (PMID 40807046, 2025).
scoliosis (1 paper, 2015). A congenital or acquired spinal deformity characterized by lateral curvature of the spine. "The presence of scoliosis was significantly associated with IL-4 (r = 0.424, P < 0.0001), IFN-γ (r = −0.458, P < 0.0001), IL-12p70 (r = −0.327, P = 0.0029), IL-4/IFN-γ ratio (r = 0.491, P < 0.0001), IL-5/IFN-γ ratio (r = 0.442, P = 0.0001), and IL-6/IFN-γ ratio (r = 0.429, P = 0.0001)." (PMID 26236424, 2015).
Seizure (1 paper, 2019). A seizure is an intermittent abnormality of nervous system physiology characterized by a transient occurrence of signs and/or symptoms due to abnormal excessive or synchronous neuronal activity in the brain. "In a study comparing serum levels of TNF-α and interleukin 4 (IL-4) in patients with febrile seizures versus controls (febrile patients without seizure or history of febrile seizures), it was found that both TNF-α and IL-4 concentrations were significantly higher in patients with febrile seizures." (PMID 31394791, 2019).
sialadenitis (1 paper, 2024). Sialadenitis is an infection of the salivary glands. "Higher IL-4 and IL-13 levels are identified in the submandibular glands (SMGs) of patients with lgG4-related sialadenitis, which induces salivary gland epithelial cell senescence through ROS/p38 MAPK-p16INK4A pathway or damaging mitochondrial functions." (PMID 38714918, 2024).
sinus disorders (1 paper, 2006). "The CRS-FA patients in this study showed an aberrant Th2 pattern immune reaction as high levels of serum antigen specific IgE, IL-4, IL-13 and low levels of IFN-γ were recorded before the treatment of their sinus disorders." (PMID 16919166, 2006).
skin abscess (1 paper, 2023). "Although the skin abscess area resulting from S. pseudintermedius infection was significantly smaller than that caused by S. aureus in mice, the expression of cytokines interleukin-4 (IL-4) and interleukin-5 (IL-5) were significantly higher in the S. pseudintermedius-infected mice." (PMID 37183254, 2023).
skin changes (1 paper, 2021). "In conclusion, this study suggested that immunotherapy against IL4/13 improved patients’ daily life which might be related with reduced pathological skin changes." (PMID 34571811, 2021).
sleep dysfunction (1 paper, 2025). "For patients treated with anti-IL-4, SNOT-22 subdomains were analyzed according to Khan’s five-domain model: rhinologic symptoms (Domain 1), extranasal rhinologic symptoms (Domain 2), ear/facial symptoms (Domain 3), sleep dysfunction (Domain 4), and psychological dysfunction (Domain 5)." (PMID 40429838, 2025).
spinal cord ischemia (1 paper, 2021). Reduced blood flow to the spinal cord which is supplied by the anterior spinal artery and the paired posterior spinal arteries. "Additionally, some studies showed that IL-4 and IL-13 suppressed the expression and production of pro-inflammatory cytokines (TNF-α and IL-1β) in the spinal cord of animal models of spinal cord ischemia." (PMID 34679060, 2021).
spondylolisthesis (1 paper, 2026). A condition in which there is forward displacement of a vertebral bone over the on below it. "IP MR identified risk-increasing associations for LSS (4E-BP1 and interleukin-4), spondylolisthesis (CXCL1, CXCL5, FGF-5, IL-15RA, and IL-4) and IDD (IL-20RA and IL-6), while IL-18 showed a protective association with IDD that remained robust after multiple-testing correction." (PMID 42317351, 2026).
stress-related disorder (1 paper, 2015). Stress-related disorders are mental health disorders that are a result of an atypical response to both short and long-term anxiety due to physical, mental, or emotional stress. "With a further study that attempts to elucidate the underlying mechanism of IL-4 and IL-10 and neuroimmune response by microglia, therapeutic intervention for stress-related disorders might be optimized." (PMID 26521132, 2015).
subarachnoid hemorrhage (1 paper, 2025). A serious neurological disorder characterized by intracranial hemorrhage into the subarachnoid space. "One study also reported higher IL-4 concentrations in the cerebrospinal fluid of patients who developed delayed ischemia, while IL-6 levels in serum on day 3 after subarachnoid hemorrhage correlated with clinical status at diagnosis and at 6 months." (PMID 40362194, 2025).
synucleinopathies (1 paper, 2017). "Both IFN-γ and TNFα have been shown to be associated with neurodegeneration in PD mouse models while the role of other cytokines, such as IL-6 and IL-4 that are upregulated in PD patients, have not been studied before in mouse models of synucleinopathies." (PMID 28049533, 2017).
T-cell deficiency (1 paper, 2022). "Partial T-cell deficiency, diminished IFN-γ cytokine and increased IL-4 production, were identified as disease-causing mechanisms." (PMID 35651609, 2022).
Taenia infection (1 paper, 2015). "Taenia infection decreased systemic levels of proinflammatory cytokines while increasing levels of IL-4 and IL-10, and the inflammatory infiltrate into the colon was also markedly reduced." (PMID 26090422, 2015).
Takotsubo syndrome (1 paper, 2021). "However, the elevated IL-2 and IL-4 levels in Takotsubo syndrome point towards activation of circulating CD4 and CD8 T cells as these are the primary source of these interleukins." (PMID 34095448, 2021). "IL-2, IL-4, IL-10, IFN-γ and TNF-α at admission were shown to be significantly higher in patients with acute Takotsubo syndrome compared to patients with AMI, conversely, IL-6 was much higher in AMI patients." (PMID 34095448, 2021).
thymic carcinoma (1 paper, 2025). Thymic carcinoma (TC) is a type of thymic epithelial neoplasm characterized by a high malignant potential. "Unexpectedly, thymic carcinoma cases exhibited a distinct cytokine milieu skewed toward type 2 inflammation, with increased levels of IL-4, IL-5, IL-9, and IL-13." (PMID 41368637, 2025). "Serum IL-18 levels were elevated—particularly in thymic carcinoma—and correlated with higher concentrations of type 2 cytokines (IL-4, IL-5, IL-9, IL-13)." (PMID 41368637, 2025).
thyrotoxicosis (1 paper, 2023). A hypermetabolic syndrome caused by the elevation of thyroid hormone levels in the serum. "Additionally, significant cytokines related to newly detected thyrotoxicosis were observed at the T2 time point, including IP-10, MDC, IL-6, and IL-4." (PMID 37629267, 2023).
toxoplasma encephalitis (1 paper, 2024). "By contrast, IL-4 is protective against the development of toxoplasma encephalitis by preventing the formation of T. gondii cysts and the proliferation of tachyzoites in the brain." (PMID 38038457, 2024).
transitional cell carcinoma (1 paper, 2022). A malignant neoplasm arising from the transitional epithelium, usually affecting the urinary bladder, ureter, or renal pelvis. "GNB3 and IL4 are both enriched in kidney diseases, transitional cell carcinoma, and neoplasm metastasis." (PMID 35565241, 2022).
trichomoniasis (1 paper, 2011). An infection that is caused by Trichomonas. "Incontrast, IL-12, IL-7, IL-10, IL-3, and IL-4 were increased in BV when comparedto control samples but not in trichomoniasis." (PMID 21572958, 2011).
tuberculous meningitis (1 paper, 2023). "They found that the level of IL-4 in the cerebrospinal fluid of patients with tuberculous meningitis was high." (PMID 37327256, 2023).
type 2 thrombocytopenia (1 paper, 2013). "In several cell lines, PaCS development follows cell differentiation/activation by trophic factors and cytokines, such as GM-CSF and IL-4 for DCs, IL-2 and IL-15 for NK cells, or thrombopoietin, IL-6 and IL-11 for megakaryocytes in type 2 thrombocytopenia." (PMID 24358206, 2013).
ureaplasma infection (1 paper, 2012). "Others have demonstrated that intra-amniotic ureaplasma infection did not result in increased levels of any tested cytokines (IL-1β, IL-1 receptor antagonist, IL-4, IL-6 and TNF-α)." (PMID 22253806, 2012).
uterine fibroids (1 paper, 2025). "In line with this, in uterine fibroids, the phagocytic ability of neutrophils is affected by the serum levels of IL-2, IL-17A, IL-6, and IL-4." (PMID 40943781, 2025).
uveal melanoma (1 paper, 2022). A melanoma derived from melanocytes of the uveal tract. "Interestingly, abnormally elevated levels of many cytokines, including IL-2, IL-4, IL-6 and IL-8, have been observed in the vitreous of eyes from patients with uveal melanoma." (PMID 35163491, 2022). "Mutation of this −280 STAT DRE totally abolished responsiveness of the HTR2B basal promoter toward IL-4 and IL-6, therefore establishing that transcription of the HTR2B gene is under the regulatory influence of STAT proteins in uveal melanoma." (PMID 35163491, 2022).
varicocele (1 paper, 2017). A condition characterized by the dilated tortuous veins of the spermatic cord with a marked left-sided predominance. "Of course, this correlation between theKIT system and cytokines in varicocele needs tobe demonstrated more comprehensively since theanalysis of only two cytokines (i.e., TNF and IL-4)are insufficient to establish this correlation." (PMID 28868836, 2017).
vascular dementia (1 paper, 2023). A degenerative vascular disorder affecting the brain. "The significantly increased serum levels of IL-4 and IL-5 in the MCI/AD group correspond with findings in a previous study that reported elevated IL-4, IL-5, IL-1β, TNF-α, IFN-γ, G-CSF, and MIF-1b levels in patients with vascular dementia." (PMID 37760836, 2023).
Vestibular schwannoma (1 paper, 2024). A vestibular schwannoma (also known as acoustic neuroma, acoustic neurinoma, or acoustic neurilemoma) is a benign, usually slow-growing tumor that develops from the VIIIth cranial nerve supplying the inner ear. "In addition, the levels of proinflammatory/proallergic cytokines (IL-4, IL-5, IL-10, and IL-13) were higher in the macula, ampulla, and endolymphatic sac dissected from patients with MD than in the specimens from patients with vestibular schwannoma." (PMID 38595846, 2024).
viral hepatitis (1 paper, 2018). An acute or chronic inflammation of the liver parenchyma caused by viruses. "IL-4-associated JHDN-5 IgG4 autoantibodies are detectable in patients with anesthetic and viral hepatitis." (PMID 30305319, 2018).
visual disorder (1 paper, 2020). "IL-4 may serve as a therapeutic target to treat this visual disorder." (PMID 32366355, 2020).
vitamin A deficiency (1 paper, 2012). Deficiency of vitamin A due to malnutrition, malabsorption, or dietary lack. "Both the number of IL-4+ T cells analyzed ex vivo and the SEA-specific IL-4 and IL-10 responses were either unaffected or only slightly reduced by vitamin A deficiency." (PMID 22927819, 2012). "By quantitative real-time PCR analysis (qRT-PCR) of isolated liver lymphocytes, we found that vitamin A deficiency significantly reduced the expression of IL-4, IL-5, and IL-13 but not of IFNγ." (PMID 22927819, 2012).
wart (1 paper, 2021). "Therefore, ex vivo quantitative analysis of IFN-γ is a reliable predictor for the appropriate therapeutic response to the promising bivalent HPV vaccine immunotherapy in wart patients, although IL-4 analysis could be a reliable predictor for the unfavorable outcome when combined with IFN-γ analysis." (PMID 34835211, 2021).
X-linked severe combined immunodeficiency (1 paper, 2021). "X-linked severe combined immunodeficiency (X-SCID) is caused by mutations of IL2RG, the gene encoding the interleukin common gamma chain (IL-2Rγ or γc) of cytokine receptors for interleukin (IL)-2, IL-4, IL-7, IL-9, IL-15, and IL-21." (PMID 34248995, 2021).